EGR1 (early growth response 1)
Diseases named in the same sentence as EGR1 in open-access papers (continued):
Sharing a sentence is not in itself a finding about the gene and the disease.
retinal degeneration (3 papers, 2012 to 2022). Degeneration of the retina. "Egr1 has been implicated in several other murine models of inherited retinal degeneration." (PMID 22363631, 2012). "While EGR1 was prominent in the inner retina of wild types, its distribution changed with retinal degeneration in rd10 mice." (PMID 35413909, 2022). "In these models, Egr1 upregulation appears to promote microglial cytotoxic activity that advances retinal degeneration." (PMID 22363631, 2012). "We hypothesize that activation of Egr1 and neurotrophic factors may represent a protective immune mechanism which contributes to the characteristically slow retinal degeneration of the rds mouse model." (PMID 22363631, 2012).
Salmonella Infections (3 papers, 2019 to 2025). Infections with bacteria of the genus SALMONELLA. "We further demonstrated that while EGR1 protein turnover is rapid, it acts as a longer-term transcriptional suppressor of inflammatory genes triggered by Salmonella infection." (PMID 41188240, 2025). "However, EGR1 has not been studied in the context of Salmonella infection of macrophages, nor has post-transcriptional regulation of Egr1 expression been studied." (PMID 41188240, 2025).
scrapie (3 papers, 2008 to 2011). A fatal disease of the nervous system in sheep and goats, characterized by pruritus, debility, and locomotor incoordination. "We have previously found the KROX family transcription factor EGR1 to be differentially expressed in microarray studies of RNA extracted from whole scrapie-infected brains." (PMID 18987751, 2008). "A recent study of microRNA signature of prion-induced neurodegeneration has shown that EGR1, E2F1 and MAZ might be also implicated in the putative deregulation of immune response related genes by miRNAs via modulation of transcriptional regulators in scrapie-infected mice." (PMID 20405009, 2010).
steatosis (3 papers, 2024 to 2025). Increased lipid within the cytoplasm of cells. "Another important finding in this study is that EtOH-fed sham mice exhibited elevated hepatic EGR1, a transcription factor that enhances liver sensitivity to LPS and regulates genes involved in inflammation, fibrosis, and steatosis." (PMID 40381698, 2025). "In accordance with the studies described previously, the upregulation of Egr1 in our study may induce protective effects against steatosis and inflammation in the liver and improve its activity in carbohydrate and fatty acid metabolism." (PMID 41373837, 2025). "A study showed that the transcriptional regulation of EGR1 could help to regulate steatosis in the liver; however, in patients with IR, the expression of EGR1 was shown to be downregulated, therefore promoting the development of steatosis and MASLD." (PMID 41373837, 2025).
subarachnoid hemorrhage (3 papers, 2017 to 2023). A serious neurological disorder characterized by intracranial hemorrhage into the subarachnoid space. "Interestingly, the loss of GCN5 activity and the induction of Egr-1, E2F1 and Bim are involved in the early brain injury (EBI) following subarachnoid haemorrhage (SAH) in rats." (PMID 28125090, 2017).
type 1 diabetes (3 papers, 2014 to 2024). "In STZ-induced type 1 diabetic mice, treatment with valsartan resulted in significantly reduced Egr-1, TF and TLR-4 in aorta." (PMID 25109475, 2014). "Recent work comparing differential gene expression across multiple autoimmune disorder datasets, including type 1 diabetes, revealed that EGR1 was the only gene commonly expressed across four datasets (type 1 diabetes, rheumatoid arthritis, systemic lupus erythematosus, Crohn's disease)." (PMID 39619154, 2024).
uveal melanoma (3 papers, 2025). A melanoma derived from melanocytes of the uveal tract. "Accordingly, lower expression of EGR1 is associated with significantly prolonged disease-free survival among uveal melanoma patients." (PMID 41154654, 2025). "In uveal melanoma, nuclear PD-L1 promotes early growth response-1 (EGR1)-mediated angiogenesis and tumorigenesis." (PMID 40726982, 2025). "Molecular analysis of uveal melanomas revealed that not only does EGR1 promote angiogenesis and tumor growth, but its expression is also strongly associated with liver metastasis." (PMID 41154654, 2025). "In uveal melanoma (UM) cells, HDAC2 inhibitors restore PD-L1 acetylation, prevent its nuclear entry, and inhibit p-STAT3 binding to the EGR1 promoter region, reducing EGR1 expression and suppressing angiogenic capacity." (PMID 40573881, 2025). "In uveal melanoma cells in particular, treatment with a MEK inhibitor results in a potent downregulation of both EGR1 and its transcriptional targets, while forced reduction in EGR1 expression was reported to attenuate growth and impart sensitivity to MEK inhibition." (PMID 41154654, 2025). "Considering the roles of EGR1 as an indicator of the MAPK cascade activity, a determinant of MEKi efficacy, and a correlate of clinical outcomes in uveal melanoma, we explored whether the addition of IMPDHi to a MEKi enhances the suppression of EGR1 expression." (PMID 41154654, 2025).
acute coronary syndrome (2 papers, 2017 to 2024). Signs and symptoms related to acute ischemia of the myocardium secondary to coronary artery disease. "The authors surmised atorvastatin's inhibitory effects on EGR1 may account for why the statin reduces inflammation in acute coronary syndromes." (PMID 39619154, 2024). "Conclusions-In acute coronary syndromes, the effects of atorvastatin on immune system might be partially related to the inhibition of the master regulator gene EGR1." (PMID 28407684, 2017). "The in-vivo effects of atorvastatin were analyzed in 10 statin-free acute coronary syndrome patients at baseline, and after 24h and 48h of atorvastatin therapy (80 mg/daily): EGR1-gene expression decreased at 24h (P = 0.01) and 48h (P = 0.005); EGR1-protein levels decreased at 48h (P = 0.03)." (PMID 28407684, 2017).
amyloid (2 papers, 2020 to 2025). "The previous implication of KLF4 and EGR1 in human AD and the conservation of this Klf4-Egr1 regulatory module across different time points and between tau- and amyloid-based AD models points to its fundamental importance in the pathological process." (PMID 40336141, 2025).
aortic valve stenosis (2 papers, 2013 to 2024). Aortic valve stenosis (AVS) is a condition characterized by narrowing of the heart's aortic valve opening. "EGR1 was shown to be upregulated in aortic valve stenosis, but AP-1 complex members have not been reported in the context of CAVD." (PMID 39766890, 2024).
autism (2 papers, 2017 to 2025). Persistent deficits in social interaction and communication and interaction as well as a markedly restricted repertoire of activity and interest as well as repetitive patterns of behavior. "Maternal diabetes–induced autism-like behaviors and social deficits in offspring are attributed to SOD2 suppression owing to OS-mediated histone methylation and the subsequent dissociation of early growth response 1 (Egr1) from the SOD2 promoter." (PMID 41511288, 2025).
autoimmune disease (2 papers, 2021 to 2024). A disorder resulting from loss of function or tissue destruction of an organ or multiple organs, arising from humoral or cellular immune responses of the individual to their own tissue constituents. "Thus, EGR1 is one of the biomarkers in autoimmune disorders and is confirmed in our study." (PMID 38956704, 2024).
brain injuries (2 papers, 2020 to 2022). "The FOS and EGR1 genes belonging to the immediate-early gene (IEG) family have been reported to be induced by a secondary insult following brain injuries." (PMID 36564820, 2022).
cholangiocarcinoma (2 papers, 2016 to 2023). A carcinoma that arises from the intrahepatic biliary tree (intrahepatic cholangiocarcinoma) or from the junction, or adjacent to the junction, of the right and left hepatic ducts (hilar cholangiocarcinoma). "Interestingly, the EGR1 gene has been previously shown to be associated with the progression of cholangiocarcinoma." (PMID 27835650, 2016). "In summary, we found ZHX1 was found to play essential roles in the proliferation, migration, and invasion of cholangiocarcinoma cells, and that its effect on the proliferation was mediated partially through EGR1." (PMID 27835650, 2016).
Crohn disease (2 papers, 2024). A gastrointestinal disorder characterized by chronic inflammation involving all layers of the intestinal wall, noncaseating granulomas affecting the intestinal wall and regional lymph nodes, and transmural fibrosis. "According to the previous literature, it was found that, in patients with IBD, the expression level of Egr1 was significantly higher in tissue with Crohn’s disease or ulcerative colitis than in adjacent normal tissue." (PMID 38672136, 2024). "However, it has been observed that, in specimens from patients with inflammation, whether from Crohn’s disease or ulcerative colitis, the expression level of Egr1 is higher compared to that of normal tissues." (PMID 38672136, 2024).
degenerative disc disease (2 papers, 2016 to 2024). "Identification of downstream signaling components within cell type-specific EGR1-dependent response pathways is expected to contribute to developing therapeutic strategies for e.g. degenerative disc disease." (PMID 26975996, 2016). "This study aimed to reveal the specific role of early growth response protein 1 (EGR1) and nuclear receptor 4A3 (NR4A3) in nucleus pulposus cells (NPCs) and the related molecular mechanism and to identify a new strategy for treating intervertebral disc degeneration (IVDD)." (PMID 38943627, 2024).
diabetic retinopathy (2 papers, 2019 to 2022). "This study focused on investigating the expression and underlying molecular mechanism of early growth response 1 (Egr1) in diabetic retinopathy." (PMID 30887692, 2019). "Studies have shown that high expression of EGR1 resulting from glucose is involved in the pathological changes in diabetic retinopathy." (PMID 35418167, 2022).
E. coli infection (2 papers, 2017 to 2024). "Meanwhile, Egr-1 also served as a master regulator in the initiation of neuroinflammatory response during meningitic E. coli infection." (PMID 38233877, 2024). "Collectively, these findings demonstrate that the disruption of BBB integrity induced by meningitic E. coli infection is dependent on the activation of Egr-1." (PMID 38233877, 2024). "These evidences indicate that ICAM-1 and VCAM-1 upregulation induced by meningitic E. coli infection depends on the activation of Egr-1." (PMID 38233877, 2024). "Furthermore, we have identified Egr-1 as a pivotal regulator of neuroinflammation elicited by meningitic E. coli infection." (PMID 38233877, 2024). "Among these, only the factors JUNB and EGR1 were also regulated during the E. coli infection." (PMID 28684793, 2017). "Therefore, we hypothesized that VEGFA, PDGFB, and ANGPTL4 may be the potential target genes of Egr-1 in meningitic E. coli infection of hBMEC." (PMID 38233877, 2024).
encephalitis (2 papers, 2022 to 2025). An acute inflammatory process affecting the brain parenchyma. "The transcriptomic analysis and mining of RNA-sequencing data combined with IPA enabled us to bioinformatically identify the DEGs consistent with EGR1 upregulation and known involvement in neuronal cell death, inflammation, and/or encephalitis." (PMID 35746681, 2022). "Ingenuity Pathway Analysis (IPA) was used to identify the DEGs following VEEV infection that were consistent with EGR1 activation, focusing on the DEGs involved in neuronal cell death, inflammation, and encephalitis." (PMID 35746681, 2022). "Because EGR1 is significantly upregulated following infection with EEEV, SINV, CHIKV, ZIKV, and RVFV and because all of these viruses are known to induce encephalitis, we next sought to examine EGR1-dependent gene expression in these viruses." (PMID 35746681, 2022). "We also examined the EGR1 gene dependency in other viruses known to induce encephalitis." (PMID 35746681, 2022). "In addition, further studies will determine if EGR1 exerts similar effects on the other EGR family members during infection with other viruses known to induce encephalitis, such as RVFV." (PMID 35746681, 2022).
endotoxemia (2 papers, 2019). "EGR1 intervention in vivo decreased host proinflammatory cytokine secretion and rescued the survival and tissue injury of the mouse endotoxemia model." (PMID 31387910, 2019). "Further, EGR1 intervention decreased host proinflammatory cytokine production level and rescued the survival of the mouse endotoxemia model." (PMID 31387910, 2019). "In conclusion, inhibition of EGR1 effectively attenuated tissue injury and improved survival in an LPS-driven endotoxemia model in mice." (PMID 31387910, 2019). "Collectively, these data provide insights into the mechanisms showing that targeting the EGR1/ADAM10 pathway may be a potential therapeutic regimen for mice with endotoxemia driven by LPS." (PMID 31387910, 2019). "ADAM10 acts as an EGR1 target gene in the mouse endotoxemia model." (PMID 31387910, 2019). "Finally, whether EGR1 intervention modulates host survival and tissue injury in an LPS-mediated mouse endotoxemia model was evaluated." (PMID 31387910, 2019). "EGR1 As-ODN rescued the survival and tissue injury in an LPS-driven mouse endotoxemia model." (PMID 31387910, 2019). "The results showed that treatment with or genetic inhibition of EGR1 triggered significant effects on cytokine and adhesion molecule expression, which further validated the functional pathway of EGR1/ADAM10 in the context of endotoxemia." (PMID 31387910, 2019).
flu (2 papers, 2021 to 2022). "Classical monocytes from patients with CAP-flu displayed upregulation of a variety of genes involved in pro-inflammatory processes, such as EGR-1, FKB5, and AREG." (PMID 34424199, 2021).
Heat Stroke (2 papers, 2016 to 2024). A condition caused by the failure of body to dissipate heat in an excessively hot environment or during PHYSICAL EXERTION in a hot environment. "In summary, EGR1 emerges as a pivotal regulator of HMOX-1 expression in KC2, orchestrating ferroptosis and NLRP3 inflammasome activation, thereby contributing to liver injury in the context of heat stroke conditions." (PMID 39309491, 2024).
Hepatitis C (2 papers, 2011 to 2025). "Egr1 itself has been implicated in Hepatitis Virus C infection through the activation of IGF-II (insulin growth factor II) gene expression, which is a critical factor during the formation of hepatocellular carinoma (HCC)." (PMID 21423752, 2011).
Huntington disease (2 papers, 2014 to 2016). Huntington disease (HD) is a rare neurodegenerative disorder of the central nervous system characterized by unwanted choreatic movements, behavioral and psychiatric disturbances and dementia. "The early growth response gene 1 (EGR1), which plays a role in memory formation, has a record-high connectivity to 13 HD-related genes and may also be considered as strong candidate for experimental confirmation of its role in the Huntington's disease." (PMID 27924190, 2016).
Hypoglycemia (2 papers, 2013 to 2023). A decreased concentration of glucose in the blood. "EGR1 upregulation in a perinatal rat model of hypoxia and hypoglycemia resulted in increased proliferation in neural progenitor cells, suggesting both of these genes promote survival in response to stressors." (PMID 37546772, 2023). "We show that Egr-1 accumulates in the nucleus of NPs as a direct consequence of hypoxia and hypoglycemia and that inhibiting Egr-1 expression decreases basal EGF-R levels and abolishes the stress-induced increase in EGF-R." (PMID 23763269, 2013). "However, following hypoglycemia and hypoxia, Egr-1 is stabilized and escapes degradation, which we have confirmed in our studies." (PMID 23763269, 2013). "Although Egr-1 has been implicated in the cellular response to hypoxia with enhanced expression of the EGF-R, we failed to see EGF-R induction in NPs when exposed to hypoxia or hypoglycemia alone." (PMID 23763269, 2013). "We show that Egr-1 expression increases in NPs, but not astrocytes, following hypoxia and hypoglycemia where it accumulates in the nucleus." (PMID 23763269, 2013).
hypoxia (2 papers, 2013 to 2025). A decrease in the amount of oxygen in the body. "In our study, the significantly increased Egr1 expression in the CO2 intoxication group (Group B) compared to the control group (Group A) may be due to respiratory center depression based on hypercarbonemia, resulting in cerebral hypoxia." (PMID 40167862, 2025).
infarction (2 papers, 2022 to 2025). A localised pathological necrosis of tissue resulting from obstruction of the blood supply usually by a thrombus, an embolus, or vascular torsion. "Knockdown of EGR1 was found to attenuate I/R-induced cardiac dysfunction and infarction area, pathological damage, and cardiomyocyte apoptosis." (PMID 35126807, 2022).
insulinoma (2 papers, 2023 to 2025). "EGR1 is induced in insulinoma cells and pancreatic β-cells following stimulation with glucose, and loss of Egr-1 in mice also appears to predispose islets to ER (endoplasmic reticulum) stress and apoptosis." (PMID 40438247, 2025). "Additionally, Egr-1 expression is upregulated in insulinoma cells after stimulation of the glucagon-like peptide-1 (GLP-1) receptor with the GLP-1 agonist exendin-4." (PMID 36614256, 2023).
intracerebral hemorrhage (2 papers, 2024 to 2025). A cerebrovascular disorder characterized by bleeding into one or both cerebral hemispheres including the basal ganglia and the cerebral cortex. "Egr-1 increases RXRa acetylation by modulating p300, thereby exacerbating cerebral injury in a rat model of intracerebral hemorrhage and dysfunction in BMECs via the STAT3/NF-κB pathway." (PMID 38233877, 2024).
invasive carcinoma (2 papers, 2009 to 2018). A carcinoma that is not confined to the epithelium, and has spread to the surrounding stroma. "EGR1 is up-regulated in the center of the cancer area of sample 3.3 and there is evidence suggesting that this gene is directly linked to the transition of the cancer into invasive carcinoma and a potential target for cancer treatment." (PMID 29925878, 2018).
leiomyoma (2 papers, 2007 to 2021). A well-circumscribed benign smooth muscle neoplasm characterized by the presence of spindle cells with cigar-shaped nuclei, interlacing fascicles, and a whorled pattern. "A total of eight leiomyoma-related DEGs (EGR1, CEBPB, IL6, PECAM1, VWF, TNFRSF1A, CD34 and ACE) were found upregulated in MF versus M only." (PMID 33807176, 2021). "Leiomyomas express these and several other transcription factors that interact with TCF8 including Runx, CITED, EGR1, EGR3, E2F1, Nurr77, c-Myc, Max, and Mad, whose expression is validated in this and our previous study." (PMID 17716379, 2007).
mental disorder (2 papers, 2015 to 2017). A disease that has its basis in the disruption of mental process. "Because EGR1 was the only gene showing the same over-expression in both SCZ fibroblasts and PBCs, its mRNA levels were also evaluated in the fibroblasts and PBCs from MDD and BD patients to determine whether EGR1 could be a specific biomarker for SCZ or is generally involved in mental disorders." (PMID 25658856, 2015).
metastatic colorectal cancer (2 papers, 2017 to 2021). "High EGR1 expression correlates with resistance to anti-EGFR treatment in vitro and poor outcome in metastatic colorectal cancer patients treated with cetuximab." (PMID 29246166, 2017).